ELP6 (elongator acetyltransferase complex subunit 6)
Description:
Component of the elongator complex which is required for multiple tRNA modifications, including mcm5U (5-methoxycarbonylmethyl uridine), mcm5s2U (5-methoxycarbonylmethyl-2-thiouridine), and ncm5U (5-carbamoylmethyl uridine). The elongator complex catalyzes formation of carboxymethyluridine in the wobble base at position 34 in tRNAs. Involved in cell migration (By similarity).
Synonyms: C3orf75; TMEM103; FLJ20211
Tractability: PROTAC: ubiquitination databases record sites on it; its protein half-life has been measured.
Gene: Protein-coding gene on chromosome 3 (47,495,640 to 47,513,712, reverse strand). Ensembl gene ENSG00000163832.
Subcellular location: Cytoplasm; Nucleus
Subcellular location (Human Protein Atlas): Cytosol; Nucleoplasm; Centrosome
Pathways (Reactome):
Chromatin organization: HATs acetylate histones
Gene Ontology:
Molecular function: protein binding
Biological process: positive regulation of cell migration; regulation of translation; tRNA wobble uridine modification
Cellular component: cytoplasm; cytosol; elongator holoenzyme complex; nucleus
Genetic constraint (gnomAD): Loss-of-function variants: 19 observed, 23.16 expected, observed/expected ratio (o/e) 0.82, 90% interval 0.57 to 1.2. The upper end of that interval is the gene's LOEUF score, 1.2, which puts it in group 5 of 6, group 1 being the genes least tolerant of losing a copy. Missense variants: 285 observed, 319.4 expected, observed/expected ratio (o/e) 0.89, 90% interval 0.81 to 0.98. Synonymous variants: 124 observed, 131.88 expected, observed/expected ratio (o/e) 0.94, 90% interval 0.81 to 1.09.
Homologues: Orthologues: chimpanzee ELP6 (99% identical), macaque ELP6 (94% identical), dog ELP6 (90% identical), pig ELP6 (85% identical), rabbit ELP6 (85% identical), mouse Elp6 (80% identical), guinea pig ELP6 (76% identical), rat Elp6 (68% identical), tropical clawed frog elp6 (58% identical), zebrafish elp6 (52% identical).
Diseases named in the same sentence as ELP6 in open-access papers:
ELP6 is named in the same sentence as 20 diseases in open-access papers, as found by Europe PMC text mining. Sharing a sentence is not in itself a finding about the gene and the disease. The quoted sentences say what the papers report.
cerebellar ataxia (3 papers, 2018 to 2023). A neurological syndrome characterized by clumsy and uncoordinated movement of the limbs, trunk, and cranial muscles. "The detected hypomorphic, missense mutation in the Elp6 gene was shown to cause Purkinje neuron (PN) degeneration, resulting in cerebellar ataxia‐like phenotype in mice." (PMID 36448458, 2023). "Here the authors identify a mutation in the Elp6 gene that contributes to the cerebellar ataxia-like phenotype in a mutant mouse." (PMID 30097576, 2018). "Our results define a mechanism in the pathology of cerebellar ataxias whereby subtle deregulation of tRNA function caused by the Elp6 mutation, leads to protein misfolding, proteome aggregation, and consecutive neuronal death resulting in a severe manifestation of the disease." (PMID 30097576, 2018). "Inhibition of microglial priming by blocking the inflammasome pathway both genetically and pharmacologically attenuated the PN degeneration and delayed the onset of ataxia in the Elp6 mutants." (PMID 36448458, 2023).
melanoma (3 papers, 2018 to 2022). A malignant, usually aggressive tumor composed of atypical, neoplastic melanocytes. "Moreover, ELP6 has been evidenced to play an important role in migration and tumorigenicity of melanoma cells, which reminded us that mutated ELP6 had a similar function in GC and thus was related to the poor prognosis of GC." (PMID 35223903, 2022). "The elongator complex protein 6 (ELP6) gene encodes an elongator subunit, which is reportedly capable of controlling cell migration and melanoma tumorigenesis." (PMID 32596958, 2020). "And ELP6 (also known as C3ORF75) has been revealed to play an important role in the migration and tumorigenicity of melanoma cells." (PMID 35223903, 2022). "In a previous study the migration and tumorigenicity of melanoma-derived cells was shown to be significantly decreased upon depletion of ELP1, ELP3, ELP5 or ELP6 in melanoma cells." (PMID 30597914, 2018).
Intellectual disability (2 papers, 2022 to 2023). "Here, we identify ELP4 and ELP6 variants in patients with developmental delay, epilepsy, intellectual disability, and motor dysfunction." (PMID 35698786, 2022).
developmental delay (1 paper, 2022). "During routine clinical examination, we identified one individual with two missense variants in ELP4 and two individuals with a missense variant in ELP6 presenting with a global developmental delay and dysmorphic features." (PMID 35698786, 2022).
Obesity (1 paper, 2024). Accumulation of substantial excess body fat. "Strikingly, GWAS studies have previously highlighted SNPs associated to phenotypes linked to inflammation and/or obesity, such as BMI and waist to hip ratio in humans for SMYD3, ELP6 and KDM1A." (PMID 38148333, 2024).
cancer (1 paper, 2021). A tumor composed of atypical neoplastic, often pleomorphic cells that invade other tissues. "While ELP4 and ELP5 mRNA expression are associated with olaparib sensitivity from univariate analysis of GDSC pan-cancer cell lines, ELP4 and ELP6 missense variants may contribute to sensitivity to olaparib in the HGSOC cell line TOV2978G." (PMID 33803939, 2021).
ELP6 also shares sentences with these, for which no sentence is quoted: microcephaly (2 papers); sterility (2); tumor (2); Ataxia (1); COVID-19 (1); endothelial dysfunction (1); epilepsy (1); gastric cancer (1); infection (1); neurologic diseases (1); pancreatic cancer (1); Rolandic epilepsy (1); schwannoma (1); systemic candidiasis (1).